IK (IK cytokine)
Description:
Involved in pre-mRNA splicing as a component of the spliceosome. Auxiliary spliceosomal protein that regulates selection of alternative splice sites in a small set of target pre-mRNA species (Probable). Required for normal mitotic cell cycle progression. Recruits MAD1L1 and MAD2L1 to kinetochores, and is required to trigger the spindle assembly checkpoint. Required for normal accumulation of SMU1. (Microbial infection) Required, together with SMU1, for normal splicing of influenza A virus NS1 pre-mRNA, which is required for the production of the exportin NS2 and for the production of influenza A virus particles. Not required for the production of VSV virus particles.
Synonyms: RED; RER; CSA2
Tractability: PROTAC: UniProt records ubiquitination sites on it; ubiquitination databases record sites on it; its protein half-life has been measured.
Target class: Other nuclear protein
Gene: Protein-coding gene on chromosome 5 (140,647,058 to 140,662,480, forward strand). Ensembl gene ENSG00000113141.
Subcellular location: Nucleus; Nucleus, nucleoplasm; Chromosome; Cytoplasm, cytoskeleton, spindle pole
Subcellular location (Human Protein Atlas): Nuclear speckles
Pathways (Reactome):
Metabolism of RNA: mRNA Splicing - Major Pathway
Gene Ontology:
Molecular function: identical protein binding; protein binding
Biological process: mitotic cell cycle; mitotic spindle assembly checkpoint signaling; mRNA splicing, via spliceosome; protein localization to kinetochore
Cellular component: chromosome; mitotic spindle pole; nuclear chromosome; nuclear speck; nucleoplasm; nucleus; U2-type precatalytic spliceosome; spindle pole
Genetic constraint (gnomAD): Loss-of-function variants: 38 observed, 64.6 expected, observed/expected ratio (o/e) 0.59, 90% interval 0.45 to 0.77. The upper end of that interval is the gene's LOEUF score, 0.77, which puts it in group 3 of 6, group 1 being the genes least tolerant of losing a copy. Missense variants: 320 observed, 525.42 expected, observed/expected ratio (o/e) 0.61, 90% interval 0.56 to 0.67. Synonymous variants: 159 observed, 170.34 expected, observed/expected ratio (o/e) 0.93, 90% interval 0.82 to 1.07.
Homologues: Orthologues: chimpanzee IK (100% identical), rabbit IK (99% identical), macaque IK (99% identical), guinea pig IK (99% identical), pig IK (99% identical), dog IK (96% identical), tropical clawed frog ik (90% identical), zebrafish ik (83% identical), Drosophila melanogaster CG14722 (8% identical), Caenorhabditis elegans Y44F5A.1 (4% identical). Paralogues in human: CSTF1 (9% identical), WDR55 (8% identical).
Diseases named in the same sentence as IK in open-access papers:
IK is named in the same sentence as 23 diseases in open-access papers, as found by Europe PMC text mining. Sharing a sentence is not in itself a finding about the gene and the disease. The quoted sentences say what the papers report.
breast carcinoma (3 papers, 2017 to 2025). "Oncogenic signalling via Ca2+‐activated K+ channels of intermediate conductance (SK4, also known as KCa3.1 or IK) has been implicated in different cancer entities including breast cancer." (PMID 28557306, 2017). "Members of the Ca2+‐activated K+ channel (KCa) family, that is BK (also known as KCa1.1, Maxi‐K or Slo1) and SK4 (also known as KCa3.1 or IK), have been implicated in the progression of malignant diseases including but not limited to gliomas, clear cell renal cell carcinoma and breast cancer." (PMID 28557306, 2017). "Ca2+-activated K+ channels of intermediate conductance (IK) are frequently overexpressed in breast cancer (BC) cells, while IK channel depletion reduces BC cell proliferation and tumorigenesis." (PMID 36302750, 2022). "However, direct evidence linking RIMS1, IK, SF3B1, and CBR1 genes specifically to lactylation modifications in breast cancer is lacking." (PMID 40406140, 2025).
depression (2 papers, 2012 to 2021). "Synaptic depression and activity-dependent, Na+-linked mechanisms including Na+/K+ ATPase pumps, IK-Na, and IKATP contribute to burst termination." (PMID 33927636, 2021).
allergic rhinitis (1 paper, 2024). Inflammation of the nasal mucous membranes caused by an IgE-mediated response to external allergens. "TRAM-34, a well-known IK inhibitor, reduced inflammation in ovalbumin-induced asthma and allergic rhinitis." (PMID 38474212, 2024). "Various studies have shown that some pore-blocking inhibitors of IK channels improved pathological conditions in immune-related diseases such as asthma, allergic rhinitis, inflammatory bowel disease, and rheumatoid arthritis." (PMID 38474212, 2024).
cardiac arrhythmia (1 paper, 2025). Any disturbances of the normal rhythmic beating of the heart or MYOCARDIAL CONTRACTION. "The downregulation of Ito and IK,ur have been described in patients as well as animal models of AF, and mutations have been linked to heritable cardiac arrhythmia." (PMID 40723857, 2025).
death (1 paper, 2022). "The increased risk of sudden cardiac death is due to an unequal elaboration of the repolarisation electrical wave in the epicardial myocardium due to a decrease in inward Na+ or Ca+2 channel currents or an increase in outward K+ currents mediated by the IK-ATP, Ito, and IK-Ach channels." (PMID 35971350, 2022).
glioma (1 paper, 2020). A benign or malignant brain and spinal cord tumor that arises from glial cells (astrocytes, oligodendrocytes, ependymal cells). "Our work revealed high levels of TNIP1 and its binding proteins, including A20 and IK, in glioma tissue, with its expression found to be negatively related to survival of glioma patients." (PMID 31691497, 2020).
leukemia (1 paper, 2023). A malignant (clonal) hematologic disorder, involving hematopoietic stem cells and characterized by the presence of primitive or atypical myeloid or lymphoid cells in the bone marrow and the blood. "We hypothesized that identified SK and IK channels could possibly be involved in the proliferation, cell viability, migration and invasion of human leukemia cells." (PMID 37367787, 2023). "The non-channel function of IK protein as a regulator of cell proliferation via ERK1/2 and JNK signaling pathways is a very intriguing discovery and this type of regulation could also work in the K562 leukemia cell line." (PMID 37367787, 2023).
partial epilepsy (1 paper, 2024). "Mutations in the KCNA1 (KV1.1) significantly reduce the amplitude of K+ currents by impacting the IK currents, thereby increasing excitability and are linked to partial epilepsy." (PMID 39375030, 2024).
cancer (8 papers, 2017 to 2024). A tumor composed of atypical neoplastic, often pleomorphic cells that invade other tissues. "Our previous investigation of the 271 EC samples from the Cancer Genome Atlas (TCGA) dataset showed that IK somatic mutations were enriched in a cluster of patients with high-grade and high-stage cancers, and this group had longer overall survival." (PMID 34065218, 2021). "The association of BK and IK channels to specific cancer hallmarks and tumor progression has already been reported for many diverse tumor cell lines such as breast, prostate, colon, glioblastoma, melanoma, cervical carcinoma, and others." (PMID 33333945, 2020). "Future studies will determine whether IK mutations can contribute to new molecular classification of EC and how IK mutations affect prognosis in a broader spectrum of cancers." (PMID 34065218, 2021). "Many studies have indicated that IK channels promote cancer progression by influencing cancer cell proliferation, cell cycle progression, invasion, metastasis, and resistance." (PMID 38474212, 2024). "Combined, these observations suggest K+ channels such as hERG1 and IK that are upregulated in several tumor entities as a very attractive target for anti-cancer therapy." (PMID 32390841, 2020). "Many studies highlighted the importance of the IK channel for the proliferation and the migration of different types of cancer cells, showing how IK blockers could slow down cancer growth." (PMID 38003471, 2023). "Similarly, this can also be supported by the fact that the ik KO embryos and IK-deficient myoblasts were not affected by apoptosis, although knockdown of IK has been reported to induce apoptosis in cancer cells." (PMID 33789631, 2021). "Up to date, the formation of the BK- or IK – Orai1 channel complexes and their potential role in cancer cell function has not yet been clarified in detail." (PMID 33333945, 2020).
tumor (6 papers, 2017 to 2022). "To address a putative link between energy metabolism and IK expression, we utilized primary murine BC cells either derived from WT or IK KO FVB/N mice of the tumor-prone MMTV-PyMT model." (PMID 36302750, 2022). "Since the highly statistically significant association between IK mutations and EC patient survival and the high fraction of loss-of function frameshift and stop-gain mutations, we hypothesized that loss of IK could have a great impact on cellular functions in EC tumor cells." (PMID 34065218, 2021). "Consistently, we found that IK mutations were associated with increased tumor mutation burden independent of mutations of BRCA and POLE, two DNA repair genes associated with tumor mutation burden in EC." (PMID 34065218, 2021). "This is in line with previous experiments demonstrating that IK inhibition or its global depletion in a FVB/N-based MMTV-PyMT model of BC improves survival and reduces cell proliferation rates in vitro and tumor growth in vivo." (PMID 36302750, 2022).
IK also shares sentences with these, for which no sentence is quoted: infection (2 papers); acute lymphoblastic leukemia (1); aortic coarctation (1); asthma (1); atrial tachycardia (1); cardiac hypertrophy (1); chlamydial infection (1); endometrial cancer (1); glioblastoma (1); melanoma (1); pancreatic cancer (1); psychosis (1); T-cell leukemia (1).